TRIM27 (tripartite motif containing 27)
Diseases named in the same sentence as TRIM27 in open-access papers (continued):
Sharing a sentence is not in itself a finding about the gene and the disease.
Crohn disease (4 papers, 2012 to 2022). A gastrointestinal disorder characterized by chronic inflammation involving all layers of the intestinal wall, noncaseating granulomas affecting the intestinal wall and regional lymph nodes, and transmural fibrosis. "Analysis of TRIM27 mRNA expression in colon biopsy material of Crohn's disease patients confirmed a significant increase in TRIM27 expression in CD compared to healthy controls." (PMID 22829933, 2012). "We found that TRIM27 expression is increased in Crohn's disease patients, underscoring a physiological role of TRIM27 in regulating NOD2 signaling." (PMID 22829933, 2012). "We identified TRIM27 as a negative regulator of NOD2-mediated inflammatory responses and detected enhanced TRIM27 expression in the colon of Crohn's disease patients." (PMID 22829933, 2012). "Accordingly, TRIM27 might affect NOD2-mediated proinflammatory responses to promote the progression of Crohn’s disease." (PMID 36200036, 2022). "An immunohistological inspection indicated that when compared to healthy tissue, TRIM27 expression appeared higher in tissue derived from patients with Crohn disease (CD), implying that TRIM27 has a role in CD, which is a known NOD2-related inflammatory disease." (PMID 34177938, 2021). "Finally, to explore if TRIM27 expression might be linked to NOD2-associated diseases in vivo, we conducted immunohistological inspection of colon sections derived from healthy and active Crohn's disease (CD) patients." (PMID 22829933, 2012). "Collectively, these data support a role for TRIM27 as a specific negative regulator of NOD2-mediated signaling and suggest a implication of TRIM27 in Crohn's disease." (PMID 22829933, 2012). "It is conceivable that targeting TRIM27 might be advantageous when NOD2 activity is altered, such as in Crohn's disease." (PMID 22829933, 2012).
melanoma (4 papers, 2019 to 2024). A malignant, usually aggressive tumor composed of atypical, neoplastic melanocytes. "The results showed that compared with normal lines, TRIM27 was highly expressed in melanoma cell line A375, and TRIM29 was downregulated in melanoma cell line A375, and both had statistical significance (p < 0.05)." (PMID 33118318, 2020). "Survival analysis suggested that the expression of TRIM27 significantly affected the overall survival and disease‐free survival of melanoma, and its expression was confirmed by qRT‐PCR." (PMID 33118318, 2020). "TRIM27 was faintly expressed in cutaneous tissues and strongly stained in slices of melanoma." (PMID 33118318, 2020). "By various data sets and comprehensive methods, we not only identified TRIMs that are differentially expressed in melanoma but also discovered that TRIM27 may be considered a new potential biomarker for melanoma." (PMID 33118318, 2020). "Our results indicated that the expression level of TRIM27 might be a prognostic marker of melanoma." (PMID 33118318, 2020). "Therefore, TRIM27 may be a prognostic biomarker for melanoma." (PMID 33118318, 2020). "In the GEPIA database, TRIM2 and TRIM27 expression were significantly higher, and TRIM7 and TRIM29 expression was significantly downregulated in melanoma; these results were consistent with data from the Oncomine database (all p < 0.05)." (PMID 33118318, 2020). "The gene expression of TRIM2 and TRIM27 was markedly higher, and the expression of TRIM7, TRIM8, and TRIM29 was significantly downregulated in melanoma." (PMID 33118318, 2020). "We used the GEPIA database to investigate the prognostic analysis of TRIM2, TRIM7, TRIM8, TRIM18 (MID1), TRIM19 (PML), TRIM27, and TRIM29 in melanoma." (PMID 33118318, 2020). "Differential expression of TRIM2, TRIM7, TRIM8, TRIM18 (MID1), TRIM19 (PML), TRIM27, and TRIM29 may play an important role in the development of melanoma." (PMID 33118318, 2020). "This profile of TRIM27 function in cancer suggests that the activity of TRIM proteins can be pleiotropic and, hence, TRIM16 may suppress cell proliferation and migration in melanoma, but has the potential to increase tumorigenesis in SCC." (PMID 31342168, 2019).
non-small cell lung carcinoma (4 papers, 2020 to 2024). A group of at least three distinct histological types of lung cancer, including non-small cell squamous cell carcinoma, adenocarcinoma, and large cell carcinoma. "TRIM47 and TRIM27 have an oncogenic role in colorectal, prostate, oesophageal, ovarian and non-small cell lung cancer, promoting proliferation and metastasis." (PMID 33772100, 2021).
bipolar disorder (3 papers, 2022 to 2025). A disorder of the brain that causes unusual shifts in mood, energy, activity levels and the ability to carry out day-to-day tasks. "TRIM27 (brain-wide MTSG P-value: 4.732 × 10-21, single tissue P-value: 1.0), second on the list, differentially expresses in SCZ and bipolar disorder patients compared to healthy control and is a risk gene identified by GWAS study for SCZ in Japanese and European ancestry." (PMID 40690510, 2025). "This analysis revealed top genes, such as NOTCH4, MICA, TRIM27, PBX2, and FKBPL, as enriched in GWAS of schizophrenia, CLZ-induced agranulocytosis/granulocytopenia in treatment-resistant schizophrenia, and bipolar disorder among other psychiatric and non-psychiatric conditions." (PMID 35664466, 2022).
colon cancer (3 papers, 2018 to 2024). "The results indicated that TRIM27-deficient mice developed less and smaller colon tumors compared with their wild-type littermates." (PMID 30143645, 2018). "In the AOM/DSS model, TRIM27-deficient mice developed less, smaller, and lower-grade colon tumors compared with their wild-type littermates." (PMID 30143645, 2018). "Immunohistochemical analysis indicated that there were less phosphorylated STAT3-positive cells in colon tumors of TRIM27-deficient mice compared to their wild-type littermates." (PMID 30143645, 2018). "Consistently, the protein levels of STAT3 downstream target genes Bcl-xl, c-Myc, Pcna, and Ccnd1, which were responsible for tumor cell survival and proliferation, respectively, were dramatically downregulated in colon tumors of TRIM27-deficient mice compared to their wild-type littermates." (PMID 30143645, 2018). "Indisulam-mediated RBM39 degradation causes splicing defects in a broad range of genes, including TRIM27, and inhibits proliferation of colon cancer cells." (PMID 39048555, 2024). "Consistently, there was a significant decrease in proliferation rates in the colon cancers of Trim27−/− mice as determined by Ki-67 nuclear staining." (PMID 30143645, 2018). "Indeed, TRIM27 has been shown to promote tumor invasion and growth in colon cancer through its promotion of the epithelial-mesenchymal transition and activation of the AKT pathway." (PMID 34284744, 2021). "Moreover, there was also a decrease in levels of inflammatory cytokines TNF-α, IL-1β, IL-6, and IL-17A in the sera or colon tissues of Trim27−/− mice, which was consistent with the decreased inflammatory cell infiltrations in colon tumors of Trim27−/− mice." (PMID 30143645, 2018). "However, similar to the molecular biological features of TRIM27 in esophageal and colon cancer, we identified similar biological functions of TRIM27 in that it is significantly elevated in RCC tissues, accelerates the pathogenesis of RCC, and predicts RCC progression and poorer survival." (PMID 34284744, 2021). "Here the authors identify TRIM27 as a positive regulator of IL-6-induced STAT3 activation through the formation of JAK1-STAT3 complex, thus impacting inflammation-induced colon cancer development." (PMID 30143645, 2018).
esophageal cancer (3 papers, 2019 to 2021). A primary or metastatic malignant neoplasm involving the esophagus. "TRIM27 expression is a known oncogene and disease progression in various cancers, such as lung, ovarian, colon, and esophageal cancer." (PMID 34284744, 2021). "TRIM27 promotes the occurrence and development of esophageal cancer by regulating the PTEN/Akt signaling pathway." (PMID 34124063, 2021).
hepatocellular carcinoma (3 papers, 2022 to 2025). A malignant tumor that arises from hepatocytes. "Finally, in hepatocellular carcinoma (HCC), USP7 seems to increase the expression of the Tripartite Motif Containing 27 (TRIM27) gene by enhancing its stability through deubiqutination." (PMID 41157055, 2025).
IgA nephropathy (3 papers, 2023 to 2025). "The association with nearest gene TRIM27 is within the MHC locus, which has been implicated in IgA nephropathy and steroid sensitive nephrotic syndrome studies." (PMID 37872228, 2023).
psoriasis (3 papers, 2022 to 2025). An autoimmune condition characterized by red, well-delineated plaques with silvery scales that are usually on the extensor surfaces and scalp. "This study indicates that TRIM27 may be involved in the development of psoriasis." (PMID 36200036, 2022). "Several SNPs used as IVs in the psoriasis MR analyses are located in or near genes with known immunological and inflammatory functions relevant to both diseases, such as IL23R, IL13, TRIM27, HLA-A, HLA-B, and TNFAIP3." (PMID 41465162, 2025). "Elevation of TRIM27 level and activation of IL-6/STAT3 signalling pathway were found in an in vivo psoriasis-like inflammation model, whereas inhibition m6A methylation strongly alleviated the inflammation." (PMID 38146129, 2023).
autism (2 papers, 2013 to 2021). Persistent deficits in social interaction and communication and interaction as well as a markedly restricted repertoire of activity and interest as well as repetitive patterns of behavior. "TRIM27 has been implicated in several cellular and disease processes, including apoptosis, spermatogenesis, muscle atrophy and autism." (PMID 34128869, 2021). "TRIM27 is a DNA-binding protein associated with the nuclear matrix and interacts with methyl-CpG-binding domain (MBD) proteins, including MBD2, MBD3 and MBD4, and rare autism-specific protein-changing alterations have been observed both in MBD3 and MBD4." (PMID 24047820, 2013).
cardiac hypertrophy (2 papers, 2022). "In this study, we explored the potential role of Trim27 in pressure overload-induced cardiac hypertrophy and the underlying mechanism." (PMID 35311628, 2022). "Therefore, we aimed to investigate the role of Trim27 in cardiac hypertrophy and the underlying mechanisms." (PMID 35311628, 2022). "In summary, our findings demonstrated that Trim27 is expected to be a potential target for the therapy of cardiac hypertrophy." (PMID 35311628, 2022). "Our data revealed that Trim27 was significantly increased in response to cardiac hypertrophy both in vivo and in vitro." (PMID 35311628, 2022). "Many studies demonstrated that TRIM27 might contribute to the progression of cancer, ischemia-reperfusion injury, cardiac hypertrophy and brain diseases." (PMID 36200036, 2022). "Mechanistically, Akt/mTOR/p70s6k may be involved in the protective role of Trim27 against cardiac hypertrophy both in vivo and in vitro." (PMID 35311628, 2022). "Trim27 may be involved in regulating the development of cardiac hypertrophy." (PMID 35311628, 2022). "In our study, we predicted that Trim27-KO may reverse TAC-induced cardiac hypertrophy." (PMID 35311628, 2022). "Moreover, Trim27-KO could alleviate the cardiac hypertrophy and cardiac fibrosis." (PMID 35311628, 2022). "Knockout of Trim27 reduced the size of cardiomyocytes and the protein expression of ANP, BNP, and β-MHC, improved cardiac function, and decreased myocardial hypertrophy (P < 0.05)." (PMID 35311628, 2022). "However, the effects of Trim27 in cardiac hypertrophy are not fully elucidated." (PMID 35311628, 2022).
COVID-19 (2 papers, 2021 to 2023). A disease caused by infection with severe acute respiratory syndrome coronavirus 2. "In addition, the expression of VANGL2 presented a reverse correlation with IFITM3, ISG15, GBP1, and TRIM27, which have been reported to play important roles in antiviral immunity in the COVID-19 patients’ database." (PMID 37352355, 2023).
diabetes (2 papers, 2022 to 2023). "In addition, Trim27 plays some roles in diseases such as lung cancer, tuberculosis, hepatitis C virus, diabetes, Parkinson’s, and allergies." (PMID 35311628, 2022).
gastric cancer (2 papers, 2022 to 2025). A primary or metastatic malignant neoplasm involving the stomach. "Moreover, the knockdown of TRIM27 increased the sensitivity of gastric cancer cells to 5-fluorouracil treatment." (PMID 36200036, 2022). "Down-regulation of TRIM27 can inhibit cell proliferation by inhibiting the Hippo-BIRC5 pathway and inducing 5-FU sensitivity in gastric cancer." (PMID 40936722, 2025).
lung adenocarcinoma (2 papers, 2020 to 2023). A carcinoma that arises from the lung and is characterized by the presence of malignant glandular epithelial cells. "Association of TRIM27 expression with clinical characteristics of 138 patients with lung adenocarcinoma." (PMID 33264103, 2020).
myocardial ischemia (2 papers, 2022 to 2026). A disorder of cardiac function caused by insufficient blood flow to the muscle tissue of the heart. "For example, TRIM27 is markedly downregulated in murine hearts subjected to myocardial ischemia/reperfusion (I/R) injury and in cardiomyocytes exposed to hypoxia/reoxygenation (H/R); cardiomyocyte‐specific TRIM27 knockout further enlarges infarct size and worsens cardiac dysfunction in I/R mice." (PMID 41510686, 2026).
osteoporosis (2 papers, 2025 to 2026). A condition of reduced bone mass, with decreased cortical thickness and a decrease in the number and size of the trabeculae of cancellous bone (but normal chemical composition), resulting in increased fracture incidence. "Like TRIM63, we expected that TRIM27 might also play an important role in osteoporosis or sarcopenia, skeletal diseases characterized by the loss of bone and muscle mass." (PMID 40251491, 2025). "Our findings revealed a novel role of TRIM27 in bone remodeling, providing valuable insights into the molecular mechanisms underlying bone-related diseases and establishing the molecular basis for a potential therapeutic target in osteoporosis." (PMID 40251491, 2025). "An ovariectomized (OVX) mouse osteoporosis model was established to analyze TRIM27 expression and bone microstructure (H&E staining)." (PMID 42267188, 2026). "Our research reveals the potential of TRIM27 in treating bone metabolism disorders and may become a potential target for the treatment of osteoporosis." (PMID 42267188, 2026). "Our results identify TRIM27 as a novel negative regulator of NF-κB in bone remodeling, suggesting that regulating TRIM27 may be useful in developing treatments for musculoskeletal diseases, such as osteoporosis." (PMID 40251491, 2025).
renal carcinoma (2 papers, 2020 to 2021). A carcinoma arising from the epithelium of the renal parenchyma or the renal pelvis. "We also analyzed the correlation between TRIM27 and NF-κB using human renal cancer tissues." (PMID 34284744, 2021). "Seven genes (TRIM8, TRIM11, TRIM16, TRIM24, TRIM27, TRIM32, and PML) were expressed in different renal cancer cell lines through the KM expression website." (PMID 33173411, 2020).
renal cell carcinoma (2 papers, 2020 to 2021). "We can see that SENP5, SENP3, UBE2I, PIAS3, TRIM27, SAE1, and CBX4 are risk factors in the development of renal cell carcinoma." (PMID 33123273, 2020). "The roles of TRIM27, a member of the TRIM super family, in renal cell carcinoma (RCC) remained unexplored." (PMID 34284744, 2021).
Sepsis (2 papers, 2024 to 2025). Sepsis is defined as life-threatening organ dysfunction caused by a dysregulated host response to infection. "Studies have shown that in LPS-induced sepsis mice, the E3 ubiquitin ligase TRIM27 is significantly upregulated and positively correlated with the degree of lung injury." (PMID 40643532, 2025). "Overexpressing NOX4 can reverse this protective effect, revealing the key role of the “TRIM27-PPARγ-NOX4” ubiquitination axis in the lung injury of sepsis." (PMID 40643532, 2025). "In a mouse model of LPS-induced sepsis-induced lung injury, reducing TRIM27 was found to alleviate sepsis-induced inflammation, oxidative stress, and cell apoptosis by inhibiting PPARγ ubiquitination and decreasing NADPH oxidase 4 (NOX4) expression." (PMID 39234245, 2024).
tuberculosis (2 papers, 2016 to 2025). A chronic, recurrent infection caused by the bacterium Mycobacterium tuberculosis. "Based on this, targeting the TRIM27-PtpA interaction interface may become a potential new strategy for the treatment of tuberculosis." (PMID 41383846, 2025). "Our study suggests a potential tuberculosis treatment via targeting of the TRIM27-PtpA interfaces." (PMID 27698396, 2016).
viral infections (2 papers, 2022). "RNA (SeV and VSV) or DNA (HSV) virus infections upregulate Siglec1 expression in macrophages and indirectly recruit TRIM27 to mediate the Ub-dependent degradation of TBK1." (PMID 36498930, 2022).
adenoma (1 paper, 2018). A neoplasm arising from the epithelium. "In addition, most of the colon adenomas in Trim27−/− mice were low-grade dysplasia, while the adenomas in their wild-type littermates were high-grade dysplasia and infiltrated with more inflammatory cells." (PMID 30143645, 2018).
Allergy (1 paper, 2013). An allergy is an immune response or reaction to substances that are usually not harmful. "Our finding has identified a potential new pathway for vitamin D affecting the immune system, allergy risk and oxidative stress via TRIM27." (PMID 23527013, 2013).
asthma (1 paper, 2022). "The role of TRIM27 in mast cell regulation indicates the potential relationship between genetic variations in TRIM27 and asthma." (PMID 35869121, 2022).
bladder cancer (1 paper, 2024). "The results indicated that among 411 cases of bladder cancer, TRIM27 gene mutations were detected in 5 patients, HDAC4 gene mutations in 4 patients, EGR2 mutations in 2 patients, and UBE2I gene mutations in 1 patient." (PMID 38911380, 2024). "This suggests that HDAC4, TRIM27, EGR2, and UBE2I exhibit a relatively low mutation rate in bladder cancer." (PMID 38911380, 2024). "We identified four key genes, HDAC4, TRIM27, EGR2, and UBE2I, that exhibited significant associations with bladder cancer prognosis." (PMID 38911380, 2024). "Gene mutation analysis indicated a relatively low mutation rate in HDAC4, TRIM27, EGR2, and UBE2I in bladder cancer." (PMID 38911380, 2024). "Our findings demonstrated that four genes, HDAC4, TRIM27, EGR2, and UBE2I, exhibited significant associations with bladder cancer prognosis." (PMID 38911380, 2024). "Notably, high expression levels of HDAC4 and TRIM27 were identified as favorable prognostic factors for bladder cancer patients, while elevated expression of EGR2 and UBE2I was associated with an unfavorable prognosis." (PMID 38911380, 2024). "We analyzed gene expression and prognostic value of SPRG and developed a SPRG signature (SPRGS) prognostic model based on four genes (HDAC4, TRIM27, EGR2, and UBE2I) in bladder cancer." (PMID 38911380, 2024).
cleft lip (1 paper, 2021). Congenital defect in the upper lip where the maxillary prominence fails to merge with the merged medial nasal prominences. "Interestingly, differential methylation of TRIM27 was reported in a study comparing cleft lip only to cleft palate only." (PMID 34055787, 2021).
diabetic kidney disease (1 paper, 2026). Progressive kidney disorder caused by vascular damage to the glomerular capillaries, in patients with diabetes mellitus. "Thus, our results suggest that TRIM27-induced glomerular endothelial cell-derived exosomes play a major role in podocyte injury by shuttling miR-486-5p in diabetic kidney disease." (PMID 41794744, 2026).
hepatitis C virus infection (1 paper, 2025). A viral infection caused by the hepatitis C virus. "TRIM27 inhibits the type I IFN response against hepatitis C virus infection by inhibiting the IRF3 and NF-κB pathways." (PMID 40251491, 2025).